BCAN-AS2 (BCAN antisense RNA 2)
Synonyms: ENST869; AL590666.2
Gene: Long non-coding RNA gene on chromosome 1 (156,614,740 to 156,661,503, reverse strand). Ensembl gene ENSG00000229953.
Diseases named in the same sentence as BCAN-AS2 in open-access papers:
BCAN-AS2 is named in the same sentence as 2 diseases in open-access papers, as found by Europe PMC text mining. Sharing a sentence is not in itself a finding about the gene and the disease.
BCAN-AS2 shares sentences with these, for which no sentence is quoted: gastric cancer (1 paper); tumor (1).